PTH (parathyroid hormone)
Diseases named in the same sentence as PTH in open-access papers (continued):
Sharing a sentence is not in itself a finding about the gene and the disease.
vitamin D deficiency (continued). "Compared with that in women with vitamin D severe deficiency, PTH was 12.08 (95%CI: 4.01, 20.14) pg/mL lower in women with vitamin D deficiency, and 27.41 (95%CI: 0.15, 54.66) pg/mL lower in women with vitamin D sufficiency." (PMID 33732216, 2021). "A correlation between eGFR and serum intact PTH concentration was identified only in participants with vitamin D deficiency according to this definition [(β = −0.154, p = 0.012]." (PMID 32582730, 2020). "By contrast, supplementation with high Ca2+ alleviated phytate-mediated pathogenic defects such as biochemical abnormalities, high PTH levels, nephrocalcinosis, renal fibrosis, vitamin D insufficiency, hypophosphatemia, and bone loss." (PMID 32271147, 2020). "Serum levels of PTH in the vitamin D-deficiency − UV irradiation group were higher than those in the other groups." (PMID 32681041, 2020). "In human research, the parathyroid hormone concentration in relation to the 25-hydroxyvitamin D concentration is used to determine vitamin D deficiency." (PMID 33109180, 2020). "Patients with vitamin D deficiency had the largest increase in PTH from 6 months, while patients with high S-25(OH)D ≥ 100 nmol/l had lowest PTH and prevalence of SHPT." (PMID 32306297, 2020). "Overall, associations between studied outcomes and combinations of vitamin D deficiency/insufficiency with the 75th PTH percentile were similar to those shown in the main analysis." (PMID 33114615, 2020). "Serum vitamin D level is inversely correlated with serum PTH level; Vitamin D insufficiency causes an increase in serum PTH and in mineral release from bone." (PMID 33126597, 2020). "In case of damage to the parathyroid glands, for instance, due to surgical manipulation, a reduction in PTH secretion is induced with a consequent sudden decrease of serum calcium levels in patients with vitamin D deficiency." (PMID 33101410, 2020). "Conversely, six patients presented low levels of PTH, three of them in association with vitamin D insufficiency." (PMID 33067526, 2020). "A Chilean survey of 66 women prior to bariatric surgery found a prevalence of more than 70% of vitamin D deficiency and 66% of increased parathyroid hormone levels." (PMID 32326591, 2020). "It is commonly associated with vitamin D deficiency and low or inappropriately normal PTH concentrations, both of which were features of this case." (PMID 32150253, 2020). "Vitamin D deficiency involves modification of calcium–phosphorus metabolism and increased secretion of PTH, which leads to increases in bone resorption and matrix demineralization." (PMID 33488605, 2020). "Second, vitamin D deficiency also causes higher secretion of parathyroid hormone (PTH) which leads to high bone turnover and increased bone resorption and eventually it will lead to bone loss or fracture." (PMID 32103764, 2020). "The objective of this study is to assess deficiency of vitamin D in otherwise healthy individuals, and to determine the response of the PTH to vitamin D deficiency." (PMID 32821633, 2020). "Taken together, these results indicate that a reduction in eGFR represents a significant risk for an increase in serum PTH concentration only when eGFR is <60 and vitamin D deficiency is present in a general Japanese population." (PMID 32582730, 2020). "Vitamin D deficiency stimulates the secretion of parathyroid hormone which, in turn, affects Ca concentration." (PMID 32723367, 2020). "In fact, it is possible that in some patients, a persistent vitamin D deficiency and long-lasting secondary hyperparathyroidism induces an autonomous secretion of PTH (i.e., tertiary hyperparathyroidism) leading to parathyroid adenoma or hyperplasia." (PMID 32148490, 2020). "Vitamin D deficiency causes secondary hyperparathyroidism; further, parathyroid hormone causes osteoblast activation." (PMID 32999682, 2020).
vitamin D deficiency (continued). "Because calcium absorption in the intestines is vitamin D-dependent in humans and many other mammals, vitamin D deficiency appears to reduce the serum calcium concentration leading to increased PTH concentrations." (PMID 33109180, 2020). "This study illustrated the 25(OH)D status, the prevalence of vitamin D deficiency and the correlation between concentrations of 25(OH)D and serum PTH in a South China population." (PMID 31988650, 2020). "Serum vitamin D deficiency prevents the intestinal tract from absorbing Ca2+ from diet, eventually leading to elevated levels of parathyroid hormone (PTH) secretion." (PMID 33409277, 2020). "Vitamin D deficiency causes an increase in the circulating PTH level that, in turn, is known to promote atherosclerosis." (PMID 33266477, 2020). "A vitamin D deficiency causes a decrease in the intestinal absorption of calcium (Ca), reducing its status and triggering the release of Parathyroid Hormone (PTH), levels of which are inversely proportional to the levels of 25(OH)D." (PMID 32121398, 2020). "Bariatric surgery is a frequent cause of secondary hyperparathyroidism in which PTH concentrations can reach extreme levels caused by severe vitamin D deficiency combined with low intake and bioavailability of dietary and supplemental calcium." (PMID 32813765, 2020). "Vitamin D deficiency is associated with an elevated PTH concentration, which increases calcium reabsorption and phosphorus excretion in the renal tubulus, and the conversion of 25-hydroxyvitamin D (25(OH)D) to active 1.25-dihydroxyvitamin D in the kidneys." (PMID 33109180, 2020). "In human research, PTH concentrations in relation to the 25(OH)D concentration commonly serve to evaluate vitamin D deficiency levels." (PMID 33109180, 2020). "BMD was directly correlated to levels of circulating vitamin D and inversely correlated with levels of parathyroid hormone (PTH), pointing to vitamin D deficiency and hyperparathyroidism as potential contributors to bone loss." (PMID 33424724, 2020). "Parathyroid hormone levels, which increase with vitamin D deficiency, and were available in all patients at follow-up, were higher in those who needed intensive care or prolonged oxygen treatment (p < 0.01)." (PMID 33489300, 2020). "In patients with vitamin D deficiency, calcium homeostasis is provided by increasing PTH secretion in the blood." (PMID 32555278, 2020). "The association between the parathyroid hormone and 25(OH)D concentrations changed at 17 ng/mL, marking the threshold for vitamin D deficiency in pet rabbits." (PMID 33109180, 2020). "Patients diagnosed with either VD-SHPT or PHPT would have an elevated PTH concentration, and many presented with vitamin D deficiency as well as a normal serum calcium concentration." (PMID 31914999, 2020). "Alterations in parathyroid hormone, vitamin D deficiency, hypomagnesemia and tissue accumulation have all been proposed." (PMID 31508432, 2019). "With respect to the proportion of subjects in the study, 97.31% showed inadequacy of AP, 83.86% vitamin D deficiency, 79.82% inadequacy of PTH, 53.81% vitamin B12 deficiency, and 26.46% calcium deficiency." (PMID 31489911, 2019). "Even though we observed a high prevalence of vitamin D deficiency and insufficiency in our study, high PTH levels were noted only in 11 (7.2%) and all of them had vitamin D levels in the deficient range." (PMID 31176378, 2019). "The skeletal effects of moderate vitamin D deficiency in adults or elderly subjects are mainly caused by an increase of the serum PTH concentration, leading to high bone turnover and associated cortical bone loss." (PMID 30321335, 2019). "Maternal laboratory findings indicated normocalcemia, but vitamin D deficiency with a high PTH level for the lactation period was observed." (PMID 30820485, 2019).
vitamin D deficiency (continued). "In case of vitamin D deficiency, bowel absorption of calcium and phosphorus is reduced and the parathyroid gland responds to low serum calcium levels by producing parathyroid hormone (PTH) to increase the serum calcium to an acceptable level." (PMID 31327969, 2019). "The level of serum PTH rises in patients with vitamin D deficiency and should be decreased with vitamin D supplementation." (PMID 30735332, 2019). "In turn, both vitamin D deficiency and increased parathyroid hormone (PTH) concentration have been reported to worsen glucose metabolism thus contributing to obesity-related glucose derangements." (PMID 31842281, 2019). "It should be noted that among adults, PTH concentration response to vitamin D deficiency also differed between sexes." (PMID 31770397, 2019). "Vitamin D deficiency leads to impaired mineralization of bone due to an inefficient absorption of dietary calcium and phosphorus and is associated with an increase in parathyroid hormone (PTH) levels." (PMID 30934881, 2019). "Chronic hypophosphataemia is usually due to diminished Pi reabsorption associated with an increase in circulating PTH levels (primary or secondary hyperparathyroidism), vitamin D deficiency or resistance." (PMID 30393837, 2019). "Blood calcium was confirmed low, with increased parathyroid hormone, moderate 25OH-vitamin D deficiency, and normal creatinine." (PMID 30729047, 2019). "Four patients presented transiently increased PTH measurements after surgery related to vitamin D deficiency and hungry bone syndrome." (PMID 31365627, 2019). "Parathyroid hormone (PTH) levels rise with vitamin D deficiency and increased parathyroid hormone levels have been evidenced to reduced insulin sensitivity." (PMID 31259115, 2019). "The clinical effect of vitamin D deficiency was thought to be theresult of reduced calcium absorption, which, in turn, increased PTH levels, butvitamin D levels in patients with valvular AF were similar to those in healthycontrols." (PMID 31719011, 2019). "We also identified 5 cases in which Ca levels were normal with low PTH levels and vitamin D deficiency." (PMID 31360455, 2019). "In subjects with SHPT due to vitamin D deficiency, supplementation with appropriate doses of calcifediol, cholecalciferol, or ergocalciferol was able to normalize the levels of 25(OH)D and PTH, although the evidence on the use of calcifediol was limited." (PMID 31064117, 2019). "In cases of vitamin D deficiency, PTH secretion is increased until 25(OH)D reaches a sufficient concentration." (PMID 30931425, 2019). "Oral cholecalciferol 2000 IU three times per week for one year was effective in treating vitamin D deficiency in hemodialysis patients but was insufficient to lower PTH levels or improve BMD." (PMID 30149605, 2018). "Vitamin D deficiency, which is a stimulator of PTH secretion, has been frequently observed in subjects with CKD7." (PMID 29348466, 2018). "In healthy controls, PTH levels were higher in subjects with mild vitamin D deficiency than those with vitamin D insufficiency, but lower than patients with severe vitamin D deficiency." (PMID 30723655, 2018). "Karefylakis et al14 assessed vitamin D status and PTH 10 years after gastric bypass and found secondary hyperparathyroidism as the clinical outcome, with 65% and 69% of the patients presenting vitamin D deficiency and high PTH, respectively." (PMID 30539982, 2018). "In all these cases, proper vitamin D supplementation led to PTH levels normalization, thus the diagnosis of secondary hyperparathyroidism due to vitamin D deficiency was made." (PMID 30409113, 2018). "The mean concentration of parathyroid hormone was higher in diabetic patients with severe vitamin D deficiency than patients with mild vitamin D deficiency and those with vitamin D insufficiency." (PMID 30723655, 2018). "Parathyroid hormone, calcium, and phosphorous levels according to vitamin D deficiency categories in diabetic patients and healthy controls." (PMID 30723655, 2018).
vitamin D deficiency (continued). "Five of the nine tested family members had vitamin D deficiency (25OHD < 30 nmol/L), three had insufficiency (< 50 nmol/L) and 6/9 members had elevated PTH and ALP levels." (PMID 29940979, 2018). "Some studies reported the effect of cholecalciferol supplement on vitamin D deficiency, PTH-lowering, and bone fracture or bone mineral density (BMD) in hemodialysis patients." (PMID 30149605, 2018). "It is well documented that increasing 25(OH)D3 serum levels in patients with vitamin D deficiency increases intestinal calcium absorption, decreases parathyroid hormone (PTH) levels, fall incidence and fracture risk, and increases muscle strength." (PMID 30031389, 2018). "A higher percentage of T2DM patients and healthy controls with severe vitamin D deficiency showed raised PTH levels." (PMID 30723655, 2018). "Not all vitamin D deficient patients have high PTH levels, a finding that supports the emergence of new criteria for vitamin D deficiency, diagnosis and treatment, and highlights the importance of testing PTH in this regard." (PMID 30723655, 2018). "Approximately 45.5% (5/11) of our participants who experienced vitamin D deficiency and elevated PTH had lower BMD at either site." (PMID 29750126, 2018). "The higher percentage of diabetic and healthy subjects with mild vitamin D deficiency had normal PTH level." (PMID 30723655, 2018). "Another study conducted on 38 children who received antiepileptic drugs and 44 healthy, 75% of patients had vitamin D deficiency, and 21% had insufficient vitamin D levels and the amounts of PTH were different between patients and controls." (PMID 29696042, 2018). "Studies have been done correlating vitamin D to physiological markers of vitamin D deficiency such as PTH, calcium and phosphate." (PMID 30305067, 2018). "Before surgery, 25 patients (11%) had normal serum PTH levels, 9 patients (4%) had insufficient 25-hydroxy vitamin D levels (20–30 ng/mL), 84 (37%) had vitamin D deficiency (<20 ng/mL), and 133 (59%) had normal vitamin D levels (30–60 ng/mL)." (PMID 29692810, 2018). "Not all vitamin D deficient individuals manifest with increased PTH levels; this response being dependent upon the severity of vitamin D deficiency." (PMID 30723655, 2018). "PTH rise in HF clinical setting is related to the impairment of acid-based homeostasis, diuretic-induced calcium loss, and vitamin D deficiency (VDD)." (PMID 29599854, 2018). "Six months after surgery, 7 (10.45%) patients had serum calcium deficiency; 4 (7.02%) had ionized calcium deficiency; 10 (18.87%) had high PTH; and 11 (52.38%) had vitamin D deficiency." (PMID 30539982, 2018). "The high prevalence of vitamin D deficiency, associated with elevated PTH over a 10-year follow-up, suggests that the dosages of calcium and vitamin D supplements prescribed were not enough for prevention and treatment in the studied population." (PMID 30539982, 2018). "Future studies are needed to address the mechanisms of how elevated PTH levels in vitamin D deficiency contribute to the progression of cardiovascular pathology." (PMID 30273386, 2018). "For example, changes in parathyroid hormone (PTH) levels, a hormone involved in bone remodeling, and Vitamin D deficiency, an important nutrient in bone metabolism, affect the synthesis and release of insulin." (PMID 29710852, 2018). "After adjustment of possible confounding factors, the highest quartiles of PTH was significantly associated with increased risk of MetS in females, while vitamin D deficiency (less than 20 ng/ml) was related to increased risk in males." (PMID 29348466, 2018). "In the 24-month follow-up, 7 (7.07%) patients had serum calcium deficiency; 11 (13.10%) ionized calcium deficiency; 20 (22.47%) high PTH; and 33 (61.11%) vitamin D insufficiency or deficiency." (PMID 30539982, 2018).
vitamin D deficiency (continued). "Evidence on elevated serum PTH, aside from the clinical conditions of abnormal serum calcium and vitamin D deficiency, has been associated with coronary heart disease and cardiovascular mortality." (PMID 29562597, 2018). "According to the physiological model, vitamin D deficiency results in increased PTH secretion in order to maintain calcium homeostasis." (PMID 30723655, 2018). "Elevated PTH was seen in 16% (14/88) of the women (PTH mean 160.7 ± 41 pg/mL, laboratory reference range 24–114 pg/mL); among those with elevated PTH, 78.6% (11/14) women had vitamin D deficiency (25(OH) D < 50 nmol/L)." (PMID 29750126, 2018). "A few cut- offs have correlated vitamin D deficiency to physiological markers such as parathyroid hormone (PTH), calcium and phosphate with varying results." (PMID 30305067, 2018). "This associates with an almost doubled prevalence of vitamin D insufficiency in RT patients and in significantly increased levels of serum PTH at the same time point of the follow-up." (PMID 29423028, 2018). "All the iPPSD4 patients in our series exhibited PTH resistance, and although the iPPSD5 patient (PHP06) initially presented elevated PTH levels, PTH normalized after correcting the vitamin D deficiency, which is consistent with secondary hyperparathyroidism." (PMID 29499646, 2018). "A study evaluating vitamin D status and its relations with ionic calcium and parathyroid hormone (PTH) in pregnant women after RYGB found vitamin D deficiency (≤20 ng/mL) or insufficiency (>20–30 ng/mL) above 70% in all trimesters." (PMID 29973985, 2018). "Among the patients who finished the study (120 months), 82.86% (n=29) had vitamin D deficiency, and 41.94% (n=13) had high PTH." (PMID 30539982, 2018). "The higher percentage of diabetic and normal subjects with mild vitamin D deficiency had a normal PTH level." (PMID 30723655, 2018). "In vivo experiments are needed to further confirm the determinant role of PTH, instead of vitamin D deficiency, in endothelial dysfunction." (PMID 30662585, 2018). "In our study, high PTH levels have been mostly found in severe vitamin D deficiency in both normal and diabetic subjects." (PMID 30723655, 2018). "They suggested that elevated PTH levels after surgery was an adaptation to bone hunger or vitamin D deficiency." (PMID 29254153, 2017). "Physiologically, vitamin D deficiency would result in reduced intestinal absorption of calcium, which, in turn, would raise parathyroid hormone (PTH) levels." (PMID 28134804, 2017). "A direct association has also been demonstrated between circulating parathyroid hormone (PTH), which increases in parallel with the severity of vitamin D deficiency, and the duration of ALS in males." (PMID 29160835, 2017). "In a cross-sectional study of 1250 postmenopausal women, bone loss and fractures were associated with elevated serum PTH and vitamin D insufficiency, particularly in those with a higher BMI." (PMID 28272298, 2017). "Hypomagnesaemia-induced impaired PTH secretion and action, relative PTH deficiency, and vitamin D deficiency are some of the other plausible causes." (PMID 29410978, 2017). "Vitamin D deficiency stimulates parathyroid adenoma growth via higher PTH levels and more parathyroid cells are needed to raise the patient’s serum calcium to the level corresponding to the increased set-point that is characteristic of the disease." (PMID 28251020, 2017). "This suggested that vitamin D deficiency was responsible for persistent PTH elevation in some patients." (PMID 29254153, 2017). "The synthesis and secretion of parathyroid hormone (PTH) is higher in those with vitamin D deficiency." (PMID 28272298, 2017). "As expected, the observed effect of vitamin D on PTH in this study is mediated through calcium since calcium levels are significantly lower in subjects with severe vitamin D deficiency leading to increased PTH levels." (PMID 28124221, 2017).